RASSF8 (Ras association domain family member 8)
Synonyms: C12orf2; HoJ-1; HOJ1
Tractability: PROTAC: ubiquitination databases record sites on it.
Gene: Protein-coding gene on chromosome 12 (25,958,068 to 26,079,892, forward strand). Ensembl gene ENSG00000123094.
Subcellular location (Human Protein Atlas): Cytosol; Mitochondria
Gene Ontology:
Molecular function: protein binding
Biological process: signal transduction
Genetic constraint (gnomAD): Loss-of-function variants: 21 observed, 45.93 expected, observed/expected ratio (o/e) 0.46, 90% interval 0.32 to 0.66. The synonymous counts are far from expectation, so gnomAD's model fits this gene poorly and the ratio says little. Missense variants: 381 observed, 476.21 expected, observed/expected ratio (o/e) 0.8, 90% interval 0.74 to 0.87. Synonymous variants: 118 observed, 169.79 expected, observed/expected ratio (o/e) 0.69, 90% interval 0.6 to 0.81.
Homologues: Orthologues: chimpanzee RASSF8 (100% identical), macaque RASSF8 (100% identical), dog RASSF8 (99% identical), pig RASSF8 (98% identical), guinea pig RASSF8 (98% identical), mouse Rassf8 (92% identical), rabbit RASSF8 (87% identical), rat Rassf8 (84% identical), tropical clawed frog RASSF8 (72% identical), zebrafish rassf8b (65% identical), zebrafish rassf8a (55% identical), Drosophila melanogaster RASSF8 (31% identical), and 1 more. Paralogues in human: RASSF7 (31% identical), RASSF10 (19% identical), RASSF9 (17% identical).
Diseases named in the same sentence as RASSF8 in open-access papers:
RASSF8 is named in the same sentence as 23 diseases in open-access papers, as found by Europe PMC text mining. Sharing a sentence is not in itself a finding about the gene and the disease. The quoted sentences say what the papers report.
gastric cancer (6 papers, 2017 to 2024). A primary or metastatic malignant neoplasm involving the stomach. "Increased expression of miR-224 targeted Ras association domain family member 8 (RASSF8) to promote gastric cancer cell growth, migration and invasion, suggesting miR-224 as a potential therapeutic target for hypoxic gastric cancer patients." (PMID 35006436, 2020). "Through target gene validation, these authors revealed that miR-224 directly targets RASFF8 (Ras association domain family member 8), stimulating p65 nuclear translocation and NF-kB transcriptional activity to confer gastric cancer cells with more aggressive phenotype." (PMID 33673376, 2021). "Similarly, HIF-1α-induced activation of miR-224 targets Ras association domain family member 8 (RASSF8), stimulating NF-κB transcriptional activity and subcellular distribution to confer gastric cancer with more aggressive phenotypes." (PMID 32014012, 2020). "Inverse to the expression of miR-224, we found that RASSF8 was downregulated in gastric cancer tissues, as well as gastric cancer tissues with lymph node metastasis." (PMID 28173803, 2017). "MiR-224 and RASSF8 were inversely expressed in human gastric cancer tissues and related to the aggressiveness of gastric cancer." (PMID 28173803, 2017). "Their results suggest that hypoxia-inducible miR-224 promotes gastric cancer cell growth by downregulating RASSF8 and acts as an oncogene, implying that inhibition of miR-224 may have potential as a therapeutic target for patients with hypoxic gastric tumours." (PMID 33673376, 2021). "MiR-224 and RASSF8 expression levels were inversely expressed in gastric cancer." (PMID 28173803, 2017). "MiR-224 and RASSF8 were inversely expressed in gastric cancer tissues." (PMID 28173803, 2017). "Finally, miR-224 was upregulated in both gastric cancer tissues and lymph node metastasis positive tissues, while RASSF8 expression was opposite to that of miR-224." (PMID 28173803, 2017). "To determine whether RASSF8 is a functional target of miR-224 in gastric cancer, we examined the roles of RASSF8 in the cell growth and invasion under hypoxia." (PMID 28173803, 2017). "Finally, the expression levels of miR-224 and RASSF8 were detected using real-time PCR in gastric cancer tissues as well as lymph node metastasis tissues." (PMID 28173803, 2017). "In gastric cancer, miR-224-5p is induced by hypoxia and HIF-1a which inhibits RASSF8 to promote cell growth, migration, and invasion." (PMID 39714200, 2024). "RASSF8 and RASSF10 suppress cell proliferation, migration and invasion in gastric cancer, lung cancer, liver cancer, cervical cancer, colorectal cancer and esophageal squamous cell carcinoma." (PMID 31768130, 2019).
lung carcinoma (5 papers, 2015 to 2019). "There is evidence that RASSF8 acts as a tumor suppressor gene in lung cancer by silencing NF-κB p65 (RelA) activation trough IKB-α25." (PMID 29440633, 2018). "In lung cancer, RASSF8 knockdown contributes to cell migration and invasion, acting as a tumor suppressor." (PMID 28173803, 2017). "Among those, RASSF8 was selected for it serves as a tumor suppresser in lung cancer." (PMID 27626930, 2016). "RASSF8 has previously been described as a candidate tumor suppressor gene in lung cancer." (PMID 26334503, 2015). "Considering that RASSF8 is a negative regulator of NF-κB transcription activity in lung cancer, we aimed to examine NF-κB transcriptional activity with a NF-κB luciferase reporter plasmid in MGC-803 and SGC-7901 cells treated with RASSF8-overexpressing plasmid or RASSF8 siRNA under hypoxia." (PMID 28173803, 2017).
cervical cancer (4 papers, 2016 to 2021). A primary or metastatic malignant neoplasm involving the cervix. "RASSF8 has been described as a potential tumor suppressor in lung carcinogenesis and cervical cancer." (PMID 33718138, 2021). "MiR-224 promotes the cell growth, migration and invasion through the downregulation of RASSF8 under hypoxia, which was in line with the results reported in the recent article that miR-224 promotes the progression of cervical cancer by directly RASSF8." (PMID 28173803, 2017). "Our findings suggest that miR-224 acts as a tumor promoter in cervical cancer, and that miR-224 and its target RASSF8 protein have potential for use as prognostic predictors or therapeutic targets in cervical cancer patients." (PMID 27626930, 2016). "Taken these results together, RASSF8 negatively regulated by miR-224 serves as a direct target of miR-224 in progression and metastasis of cervical cancer cells." (PMID 27626930, 2016). "In this study, we demonstrated an upregulation of miR-224 and a downregulation of RASSF8 in cervical cancer tissues." (PMID 27626930, 2016). "Our findings suggest that miR-224 directly targets RASSF8 and thereby acts as a tumor promoter in cervical cancer progression." (PMID 27626930, 2016). "Further, RASSF8 knockdown by specific RNAi showed similar effects in cervical cancer cells transfected with miR-224 mimic." (PMID 27626930, 2016). "We also confirmed by bioinformatic analysis and luciferase reporter assay that miR-224 directly targeted RASSF8, a tumor suppressor, and played an oncogenic role in the progression of cervical cancer." (PMID 27626930, 2016). "We examined the protein and mRNA levels of RASSF8 expression in cervical tissues by immunohistochemistry and Realtime PCR respectively in cervical cancer(n = 25) and normal tissues(n = 25)." (PMID 27626930, 2016). "Thus, we confirmed that RASSF8 is a direct target for miR-224 and mediates miR-224 promotion of cervical cancer progression." (PMID 27626930, 2016). "Thus our in vivo experiments confirm that RASSF8 serve as a target of miR-224 participated in tumor progression in cervical cancer." (PMID 27626930, 2016). "By directly targeting RASSF8 and inhibiting RASSF8 expression, upregulated miR-224 enhances proliferation, migration, and invasion of cervical cancer cells, and consequently promotes the progression of cervical cancer." (PMID 27626930, 2016).
colorectal cancer (4 papers, 2016 to 2023). A primary or metastatic malignant neoplasm that affects the colon or rectum. "On the contrary, MEK/ERK inhibitor Ras Association Domain Family Member 2 (RASSF2) is targeted by miR-200a, miR-200c, miR-141 in colorectal cancer, and Ras Association Domain-Containing Protein 8 (RASSF8) by miR-429 in non-small lung carcinoma which results in increased proliferation." (PMID 36158660, 2022). "Methotrexate and melphalan were widely used anti-cancer agents, and MiR-505 mediates methotrexate resistance in colorectal cancer by targeting RASSF8." (PMID 37550605, 2023).
esophageal squamous cell carcinoma (4 papers, 2016 to 2019). Esophageal squamous cell carcinoma (ESCC) is a type of esophageal carcinoma (EC) that can affect any part of the esophagus, but is usually located in the upper or middle third. "RASSF8 downregulation enhances lymphangiogenesis and metastasis in esophageal squamous cell carcinoma (ESCC) and inversely correlates with patients’ survival." (PMID 28173803, 2017). "Interestingly, a recent study showed that RAS association domain family 8 (RASSF8) downregulation increases VEGF-C expression, promotes lymphangiogenesis and lymph node metastasis, and is associated with poor patient survival in esophageal squamous cell carcinoma." (PMID 27486768, 2016).
cutaneous melanoma (2 papers, 2015 to 2017). A primary melanoma arising from atypical melanocytes in the skin. "In cutaneous melanoma, RASSF8 knockdown promotes the cell growth, migration and invasion by increasing the expression of NF-κB p65." (PMID 28173803, 2017). "This is the first report on methylation of RASSF8 in cutaneous melanoma as a metastasis progression factor." (PMID 26334503, 2015). "RASSF8 has the potential of being used as a theranostic factor to treat and predict the progression of cutaneous melanoma." (PMID 26334503, 2015). "Previously, we identified RASSF8 (HOJ1, NCBI Gene ID:11228) expression in cutaneous melanoma; however the functional role of RASSF8 in melanoma is not known." (PMID 26334503, 2015).
Epithelial Ovarian Cancer (2 papers, 2021 to 2024). "For example, miR-320a promotes the proliferation and invasion of epithelial ovarian cancer cells by targeting RASSF8." (PMID 38166541, 2024).
leukaemias (2 papers, 2009 to 2015). "Hypermethylation of the RASSF8 CpG island and loss of RASSF8 expression was observed in 2/6 leukaemia cell lines." (PMID 19570220, 2009). "RASSF8 methylation was found to be infrequent, occurring in 2/6 leukaemia cell lines, 2/19 (10%) childhood T-ALLs, and 4/46 (9%) B-ALL with no methylation detectable in normal bone marrow or normal blood (0/7)." (PMID 19570220, 2009). "RASSF8 methylation was reported in a small subset of leukemia." (PMID 25750636, 2015). "However, since we observed RASSF8 CpG island hypermethylation in only 2/19 T-ALLs and 4/46 B-ALLs we suspect inactivation of RASSF8 may be involved in the pathogenesis of only a small subset of leukaemias." (PMID 19570220, 2009).
lung adenocarcinoma (2 papers, 2025). A carcinoma that arises from the lung and is characterized by the presence of malignant glandular epithelial cells. "Also, a previous study has verified that RBM15 regulates Ras association domain family 8 (RASSF8) stability via m6A modification to facilitate lung adenocarcinoma progression, which demonstrates RBM15 mediates the m6A modification of other mRNAs." (PMID 40592832, 2025). "Ma MS and colleagues found that RBM15 -mediated m6A modification could stabilize the expression of RASSF8, thereby exacerbating the progression of lung adenocarcinoma cells." (PMID 40830812, 2025).
melanoma (2 papers, 2015 to 2021). A malignant, usually aggressive tumor composed of atypical, neoplastic melanocytes. "Overall survival of melanoma patients with high RASSF8 expression was better than those with low RASSF8 expression." (PMID 34639015, 2021). "RASSF8 expression was found significantly lower in metastatic melanoma cell lines compared with primary melanoma/melanocyte cell lines." (PMID 34639015, 2021). "Metastatic melanoma tissues had significantly higher hypermethylation levels of RASSF8 compared with earlier stage tumors." (PMID 34639015, 2021). "The same inverse correlation was seen in melanoma tissues: RASSF8 expression was lower in stage III/IV advanced melanomas than in stage I/II early melanomas." (PMID 34639015, 2021). "Injection of nude mice with a melanoma cell line expressing high levels of RASSF8 or the same cell line with RASSF8 shRNA resulted in an increased tumor growth and size in the latter group." (PMID 34639015, 2021). "The analysis of the Cancer Genome Atlas (TCGA) data also showed significantly lower RASSF8 mRNA expression in systemic melanoma metastasis than in regional lymph node metastasis or primary melanomas." (PMID 26334503, 2015). "To examine RASSF8 protein expression in melanoma tissues of different AJCC stages, we performed IHC in our well clinically annotated melanoma PEAT and TMA." (PMID 26334503, 2015). "There is significantly lower RASSF8 expression in advanced melanoma compared to early stage melanoma." (PMID 26334503, 2015). "Decreased expression of RASSF8 due to methylation was also found to be related to progression of melanoma." (PMID 26334503, 2015). "In comparison to early stage melanoma, promoter region methylation in advanced melanoma resulted in lower expression of RASSF8." (PMID 26334503, 2015). "Results indicated that RASSF8 expression was low in metastatic melanoma lines and decreased with melanoma progression." (PMID 26334503, 2015). "We then explored the mechanism of RASSF8 downregulation in melanoma by assessing methylation of RASSF8 and demonstrated that methylation of RASSF8 gene promoter was higher in advanced than in early stages melanomas." (PMID 26334503, 2015). "Results from IHC show a significantly lower RASSF8 expression in AJCC stage IV melanomas, compared to AJCC stage I, II and III melanomas." (PMID 26334503, 2015). "RASSF8 expression appears significantly lower in stage IV than that in stage III melanomas in the TMA." (PMID 26334503, 2015). "Here, we have shown RASSF8-induced P65 expression, leading to inhibition of growth, migration and invasion of melanoma cells." (PMID 26334503, 2015). "Both in vivo and in vitro studies show inhibition of melanoma cells’ growth, migration and invasion as a result of RASSF8 expression downregulating P65." (PMID 26334503, 2015). "The biological and physiological roles of RASSF8 in melanoma are poorly understood; consequently there have been no comprehensive reports on RASSF8's expression and its function in melanoma cells up to date." (PMID 26334503, 2015). "RASSF8 exerts its effect on melanoma via regulation of P65 expression and the downstream target IL-6, thereby controlling tumor cell growth, migration and invasion." (PMID 26334503, 2015). "To assess localization of RASSF8 protein in melanoma cell lines, we performed immunofluorescence (IF) staining." (PMID 26334503, 2015). "Here we have demonstrated RASSF8 knockdown leading to the significant increase in growth rate and tumorigenicity of a human melanoma cells in a nude mice xenograft model." (PMID 26334503, 2015). "Overexpression of RASSF8 induced G1/S arrest and apoptosis in melanoma cells." (PMID 26334503, 2015).
melanoma (continued). "Altogether, our findings suggest that RASSF8 has a tumor suppressor role in melanoma." (PMID 26334503, 2015). "Re-expression of RASSF8 can be induced by treatment of 5-aza in melanoma cell lines." (PMID 26334503, 2015). "To further explore the role of RASSF8 in melanoma cells, we examined cell cycle and apoptosis." (PMID 26334503, 2015). "RASSF8 protein is present in both the cytoplasm and nucleus of melanoma cells." (PMID 26334503, 2015). "Our study also confirms that methylation of RASSF8 promoter occurs in advanced melanoma." (PMID 26334503, 2015). "In the present study, we investigated the expression and functional role of RASSF8 in melanoma." (PMID 26334503, 2015). "RASSF8 expression was assessed in melanoma cell lines and tumors of different AJCC stages." (PMID 26334503, 2015). "However, no functional studies had been conducted on RASSF8 in melanoma until now." (PMID 26334503, 2015).
metastatic melanoma (2 papers, 2015 to 2021). A melanoma that has spread from its primary site to another anatomic site. "TCGA data analysis show significantly higher hypermethylation of RASSF8 in metastatic melanoma tissues, than earlier stage tumors." (PMID 26334503, 2015). "The results indicated that there was lower RASSF8 expression in metastatic melanoma lines than that in the melanocyte and primary cell lines." (PMID 26334503, 2015). "Moreover, western blot analysis confirmed lower RASSF8 protein expression in most of the metastatic melanoma lines." (PMID 26334503, 2015).
bone osteosarcoma (1 paper, 2024). A usually aggressive malignant bone-forming mesenchymal neoplasm arising from the bone. "Similarly, no endogenous RASSF3 or RASSF8 were detected in U2OS cells, a human bone osteosarcoma epithelial line that is highly efficacious to study Hippo signaling." (PMID 39009833, 2024).
Infertility (1 paper, 2025). "Some infertility-related genes were identified in these networks, including DAZ family genes (DAZ1, DAZ3, and DAZ4), NF1 family TF motifs (NFIX), and ras association domain family 8 (RASSF8)." (PMID 40391511, 2025).
non-small cell lung carcinoma (1 paper, 2022). A group of at least three distinct histological types of lung cancer, including non-small cell squamous cell carcinoma, adenocarcinoma, and large cell carcinoma. "For instance, circPTPRA acts as a competitive endogenous RNA (ceRNA) against miR-96-5p to erase the repressive role of RASSF8, consequently suppressing epithelial-mesenchymal transition and metastasis of non-small cell lung carcinoma (NSCLC)." (PMID 35668527, 2022).
osteosarcoma (1 paper, 2022). A usually aggressive malignant bone-forming mesenchymal neoplasm, predominantly affecting adolescents and young adults. "Furthermore, miR-505-5p level in osteosarcoma significantly elevated, whereas inhibiting miR-505-5p upregulated RASSF8, thus inhibiting osteosarcoma cell proliferation and promote their apoptosis." (PMID 36225178, 2022).
rotator cuff tears (1 paper, 2023). "In conclusion, we have identified S100A1 and RASSF8 as potential therapeutic targets for rotator cuff tears." (PMID 37601265, 2023). "In addition, through animal experiments, it was found that Butanediamide can significantly inhibit the expression of S100A1 and RASSF8, and promote healing of rotator cuff tears." (PMID 37601265, 2023). "In summary, both S100A1 and RASSF8 may promote the healing of rotator cuff tears by enhancing angiogenesis and inhibiting cell apoptosis." (PMID 37601265, 2023). "In summary, this study offers new understanding into the possible use of FDA-approved drugs as treatment options for rotator cuff tears by focusing on the key proteins S100A1 and RASSF8." (PMID 37601265, 2023).
squamous cell carcinoma (1 paper, 2016). A carcinoma arising from squamous epithelial cells. "Based on these observations, the authors suggested that downregulated RASSF8 may be a biomarker for poor outcome and a therapeutic target in squamous cell carcinoma." (PMID 27486768, 2016).